GIGYF2 (GRB10 interacting GYF protein 2)
Diseases named in the same sentence as GIGYF2 in open-access papers:
GIGYF2 is named in the same sentence as 36 diseases in open-access papers, as found by Europe PMC text mining. Sharing a sentence is not in itself a finding about the gene and the disease. The quoted sentences say what the papers report.
Parkinson disease (16 papers, 2014 to 2025). A progressive degenerative disorder of the central nervous system characterized by loss of dopamine producing neurons in the substantia nigra and the presence of Lewy bodies in the substantia nigra and locus coeruleus. "Various genetic variants of GIGYF2 have been implicated in schizophrenia and neurodegenerative diseases such as Parkinson’s disease and dementia with Lewy bodies." (PMID 40943654, 2025). "The Grb10-Interacting GYF Protein 2 (GIGYF2) gene is located on human chromosome 2q37, a region linked to familial Parkinson’s disease, and an intimate association between GIGYF2 mutations and Parkinson’s disease has been revealed." (PMID 39138413, 2024). "A number of studies have found variants in GIGYF2 potentially associated with an autosomal dominant form of Parkinson’s disease, particularly in European populations but not in Asian cohorts." (PMID 38418088, 2024). "In humans, heterozygous mutation of the GIGYF2 gene has been linked to familial Parkinson’s disease." (PMID 34502507, 2021). "Mutations in another SMY2-type GYF protein GIGYF2 (Grb10-Interacting GYF Protein 2) have debatably been reported to associate with Parkinson's disease." (PMID 28362261, 2017). "GIGYF2 variants are of interest for their important role in familial Parkinson’s disease." (PMID 37730603, 2023). "There is evidence that protein Grb10-interacting GYF protein 2 (GIGYF2), a protein associated with Parkinson’s disease, has four typical AKT consensus site motifs, which can modulate AKT signaling, although it is not clear whether GIGYF2 is a substrate of AKT." (PMID 35111368, 2022). "Most recently, several lines of evidence have shown that GIGYF2 gene mutations are closely linked to human familial Parkinson's disease, one of the most common neurodegenerative disorders, thus further supporting the notion that GIGYF2 may play a critical role in neuronal degradation in CNS." (PMID 25268761, 2014). "There appears to be a direct link to GIGYF2′s ability to interact with RNA-binding factors, as mutation of the GYF domain was linked to late-onset Parkinson’s disease in a Spanish family." (PMID 34502507, 2021). "At least 19 genetic loci for Parkinsonism have been identified to date, ten of which are autosomal dominant genes: SNCA (PARK1/PARK4), PARK3, UCHL1 (PARK5), LRRK2 (PARK8), GIGYF2 (PARK11), HTRA2 (PARK13), VPS35 (PARK17), EIF4G1 (PARK18), TMEM230 (PARK21), and CHCHD2 (PARK22)." (PMID 34356877, 2021).
Cognitive impairment (4 papers, 2014 to 2025). Abnormal cognition is characterized by deficits in thinking, reasoning, or remembering. "Grb10-interacting GYF Protein 2 (GIGYF2), an RNA-binding protein, is widely expressed in various tissues including the liver, and has been implicated in diabetes-induced cognitive impairment." (PMID 39138413, 2024). "It remains unknown whether endogenous GIGYF2 expression contributes to the development of diabetes-associated cognitive impairment." (PMID 25268761, 2014). "Our findings suggest that GIGYF2 may play an important role in the development of diabetes-associated cognitive impairment through modulating the phosphorylation of IGF1R and its downstream ERK1/2 signaling pathway, but not Akt signaling pathway." (PMID 25268761, 2014). "Our results revealed that the level of GIGYF2 expression was significantly up-regulated in hippocampus tissue of diabetic mice, which is correlated with manifestations of diabetes-associated cognitive impairment." (PMID 25268761, 2014). "Down-regulation of GIGYF2 expression may provide a potential novel approach to treat diabetes-associated cognitive impairment caused by aberrant IGF1R signaling pathway." (PMID 25268761, 2014). "Furthermore, elevated GIGYF2 expression may facilitate the development of diabetes-associated cognitive impairment by negatively regulating the IGF1R signaling pathway." (PMID 39138413, 2024). "Therefore, down-regulation of GIGYF2 expression may provide a potential novel approach to treat diabetes-associated cognitive impairment caused by aberrant IGF1R signaling pathway." (PMID 25268761, 2014). "Studies on mouse models explored cognitive impairment as a complication of diabetes through the repression of IGF-1R by GIGYF2." (PMID 40523800, 2025).
autism (3 papers, 2022 to 2025). Persistent deficits in social interaction and communication and interaction as well as a markedly restricted repertoire of activity and interest as well as repetitive patterns of behavior. "Our findings are consistent with the involvement of 4EHP/GIGYF2 in the etiology of autism in humans." (PMID 40523800, 2025). "Mutations in the genes encoding various factors that regulate translation (eIF4E, eIF4G1, GRB10‐interacting GYF protein 1 (GIGYF1), GIGYF2, and zinc finger protein 598) were identified in people with autism (Simons Foundation Autism Research Initiative, SFARI database)." (PMID 41236931, 2025).
diabetes (3 papers, 2014 to 2025). "Based on these contexts, here we sought to elucidate the role of GIGYF2 and its underlying mechanism of action in modulating insulin resistance and diabetes development in the context of obesity." (PMID 39138413, 2024). "Functionally, knockdown of GIGYF2 expression markedly ameliorated diabetes-associated cognitive dysfunction as well as the ultrastructural pathology and abnormal neurobehavioral changes." (PMID 25268761, 2014). "Targeting GIGYF2 may represent a promising therapeutic approach for the treatment of IR-related diabetes." (PMID 39138413, 2024). "Previous studies have demonstrated that the expression level of IGF1 and IGF1R decreased in brain tissue of diabetes, and disruption of the GIGYF2 gene in mice led to a decrease in IGF1-stimulated IGF1R tyrosine phosphorylation but an augmentation in ERK1/2 phosphorylation." (PMID 25268761, 2014). "However, the pathophysiological function of GIGYF2, particularly its role in the aberrant IGF1R signaling pathway in diabetes, remains largely unknown." (PMID 25268761, 2014).
Insulin resistance (2 papers, 2024 to 2025). Increased resistance towards insulin, that is, diminished effectiveness of insulin in reducing blood glucose levels. "GIGYF2 was shown to cause insulin resistance in obese mice by impairing the phosphoinositide 3-kinase/protein kinase B (PI3K/AKT) pathway, which facilitates the translocation of glucose transporter GLUT4 from the cytoplasm to the cell membrane." (PMID 40523800, 2025).
Macrocephaly (2 papers, 2018 to 2021). Occipitofrontal (head) circumference greater than 97th centile compared to appropriate, age matched, sex-matched normal standards. "We identified a potential novel risk gene (ZNF292), one novel gene with recurrent LGD DNMs (RALGAPB), as well as genes associated with macrocephaly (GIGYF2 and WDFY3)." (PMID 30564305, 2018). "For example, GIGYF2 was identified to be associated with macrocephaly." (PMID 33867917, 2021).
viral infection (2 papers, 2025). "While GIGYF2 has been implicated in diverse pathological conditions, including metabolic diseases, vascular aging, viral infections, and neurodegenerative disorders, the molecular mechanisms identified in disease contexts remain limited and often correlative rather than mechanistically definitive." (PMID 40643551, 2025). "Additionally, dysregulation of GIGYF2 has been implicated in various pathological conditions, including metabolic diseases, vascular aging, viral infections, and neurodegenerative disorders." (PMID 40643551, 2025). "To understand the molecular mechanism by which GIGYF2 supports viral replication, we set out to identify GIGYF2 targets in the context of viral infection." (PMID 40705924, 2025). "From metabolic disorders to vascular aging, viral infections, and neurodegenerative disorders, aberrant GIGYF2 activity contributes to disease progression through disruption of essential regulatory mechanisms." (PMID 40643551, 2025). "The subsequent section examines the evidence linking GIGYF2 to specific pathological conditions, including metabolic diseases, vascular aging, viral infections, and neurodegenerative disorders, thereby elucidating the clinical implications of this molecular regulator." (PMID 40643551, 2025). "Next, we investigated the subcellular localization of GIGYF2 following virus infection." (PMID 40705924, 2025). "Our work underscores the importance of Nsp2 and GIGYF2 in viral infection." (PMID 40705924, 2025). "Similar to the co-localization of GIGYF2 and Nsp2 near the DMVs, ZNF598 also co-localized with Nsp2 specifically upon viral infection." (PMID 40705924, 2025). "In viral infections, SARS-CoV-2 protein NSP2 directly interacts with human GIGYF2, enhancing the binding of GIGYF2 to 4EHP and partially increasing GIGYF2-mediated miRNA translation suppression." (PMID 40643551, 2025).
breast carcinoma (1 paper, 2014). "Previous studies have shown that knockdown of GIGYF2 resulted in a significant reduction of the phosphorylation of AKT in breast cancer cell lines." (PMID 25348067, 2014).
breast tumor (1 paper, 2014). "The Ridaifen B (RID-B), a tamoxifen derivative that potently inhibits breast tumor growth, can directly bind to GIGYF2 and subsequently inhibit GIGYF2-induced Akt phosphorylation." (PMID 25268761, 2014).
diabetic encephalopathy (1 paper, 2014). A brain disease that is characterized by functional impairment of cognition, cerebral signal conduction, neurotransmission and synaptic plasticity, and underlying structural pathology associated with diabetes. "Based on these findings, we can speculate that, in diabetic encephalopathy, the effect of GIGYF2 on IGF1R signaling is not only mediated by cooperation with Grb10, but also by interaction with some other molecules." (PMID 25268761, 2014).
epithelial ovarian cancer (1 paper, 2024). "This investigation showcased a comprehensive genome-wide methylation profile of epithelial ovarian cancer (EOC) and identified six hypermethylated/downregulated genes, (POLR3B, PLXND1, GIGYF2, CRKL, STK4, and BMP2) as potential diagnostic targets." (PMID 38627856, 2024). "POLR3B and GIGYF2, identified as novel hypermethylated genes, might serve as promising biomarkers for diagnosing and predicting the prognosis of ovarian cancer." (PMID 38627856, 2024).
Glucose intolerance (1 paper, 2024). Glucose intolerance (GI) can be defined as dysglycemia that comprises both prediabetes and diabetes. "Moreover, in obese mice, disruption of GIGYF2 also attenuates HFD-induced glucose intolerance and IR." (PMID 39138413, 2024). "In the in vivo mice model, GIGYF2 knockdown and tocopherol administration alleviate high-fat diet (HFD)-induced glucose intolerance and IR, along with the suppression of STAU1/PTEN and restoration of PI3K/AKT signaling." (PMID 39138413, 2024).
leukemia (1 paper, 2019). A malignant (clonal) hematologic disorder, involving hematopoietic stem cells and characterized by the presence of primitive or atypical myeloid or lymphoid cells in the bone marrow and the blood. "Each validated gene in this category, i.e., CD3G, DFFA, GIGYF1, GIGYF2, and INTS3 were shown to play a role in neoplastic processes, including leukemia." (PMID 31709175, 2019).
myxoma (1 paper, 2023). A benign soft tissue neoplasm characterized by the presence of spindle and stellate cells, lobulated growth pattern, and myxoid stroma formation. "In the present study, only one missense mutation of GIGYF2 was identified with no clear relation to myxoma." (PMID 38310436, 2023).
Obesity (1 paper, 2024). Accumulation of substantial excess body fat. "In the current study, we revealed that obesity leads to IR via upregulating GIGYF2 expression, which causes the disruption of the PI3K/AKT pathway through activation of the STAU1-PTEN signaling cascade." (PMID 39138413, 2024). "Further investigation remains warranted to determine whether GIGYF2 mediating PA-associated lipid homeostasis contributes to obesity-related IR." (PMID 39138413, 2024). "Here, we demonstrate that dysregulated expression of GIGYF2 is involved in the modulation of obesity-induced IR." (PMID 39138413, 2024). "Our study discloses that GIGYF2 mediates obesity-related IR by disrupting the PI3K/AKT signaling axis through the up-regulation of STAU1/PTEN." (PMID 39138413, 2024). "Targeting GIGYF2 may offer a potential strategy for treating obesity-related metabolic diseases, including type 2 diabetes." (PMID 39138413, 2024). "This study discloses a novel regulatory mechanism for GIGYF2 regulating obesity-induced IR and T2D." (PMID 39138413, 2024). "In summary, our study disclosed a novel function for the gene GIGYF2 in obesity-induced IR." (PMID 39138413, 2024). "Nevertheless, the investigation into how GIGYF2 regulates obesity-related IR remains unclear." (PMID 39138413, 2024). "Based on the in vitro findings that GIGYF2 promotes IR in hepatocytes through the STAU1/PTEN/AKT axis, we therefore further investigated whether GIGYF2 mediates obesity-induced IR in obese mice fed with HFD." (PMID 39138413, 2024).
psychosis (1 paper, 2025). "Similarly, a recent case reported a patient with neurodegeneration who carried a p.Pro380Arg mutation in the GIGYF2 gene, which encodes Grb-10 interacting GYF protein-2, as well as a duplication in the 22q11.2 region, and who presented with psychosis and early-onset dementia." (PMID 40943654, 2025).
cancer (4 papers, 2017 to 2025). A tumor composed of atypical neoplastic, often pleomorphic cells that invade other tissues. "In the COSMIC database, GIGYF2 is not a known cancer gene, and the missense mutation rate is 51.98%." (PMID 38310436, 2023). "One sub-network (network index 8) includes two cancer genes PABPC1, GIGYF2." (PMID 28415609, 2017).
infection (4 papers, 2019 to 2025). The state of being infected such as from the introduction of a foreign agent such as serum, vaccine, antigenic substance or organism. "A recent genetic screen has revealed that both 4EHP and GIGYF2 are necessary for infection by SARS-CoV-2 in vitro, while dispensable for seasonal coronaviruses." (PMID 35756894, 2022). "Notably, our data demonstrate that SARS-CoV-2 Nsp2 relocates GIGYF2 from a diffuse cytosolic distribution to the vicinity of DMVs during infection." (PMID 40705924, 2025). "Upon infection, GIGYF2 and ZNF598 relocate to areas near DMVs, viral replication sites." (PMID 40705924, 2025). "The recent discovery that 4EHP and GIGYF2 are needed for infection by SARS-CoV-2 could reinforce this idea, although further research will be required to test this possibility." (PMID 35756894, 2022). "The number of cells positive for the viral protein E in cells depleted of GIGYF2 or TIMP4 was either similar or higher compared to that of control cells upon YFV or WNV infection, suggesting that these two candidates are dispensable for replication of both viruses." (PMID 30650657, 2019). "Furthermore, we generated GIGYF2 KO cells by introducing CRISPR–Cas9 into Calu-3 and 293T-ACE2 cells and measured viral RNA levels in single-cycle infection conditions." (PMID 40705924, 2025). "When we visualized endogenous GIGYF2 without infection, it was spread throughout the cytoplasm." (PMID 40705924, 2025). "Combined with our immunocytochemistry results and tethering experiments, this suggests that while Nsp2 recruits GIGYF2 near DMVs to increase GIGYF2’s local concentration during infection, Nsp2 is not required for GIGYF2 activity per se under uninfected conditions." (PMID 40705924, 2025).
neurodegenerative disease (3 papers, 2016 to 2025). A disorder of the central nervous system characterized by gradual and progressive loss of neural tissue and neurologic function. "Thus, by acting to minimise (via the GIGYF2 limb) and resolve (via the ZNF598 limb) ribosome collisions, both pathways seem to protect the proteome from detrimental translation products that may contribute to neurodegenerative disease." (PMID 32657267, 2020).
metabolic disease (2 papers, 2024 to 2025). A congenital disorder (due to inherited enzyme abnormality) or acquired (due to failure of a metabolically important organ) disorder resulting from an abnormal metabolic process. "In metabolic diseases, particularly hepatic insulin resistance and type 2 diabetes, GIGYF2 functions as an RNA-binding protein that enhances STAU1 mRNA stability." (PMID 40643551, 2025).
neurological disorders (1 paper, 2021). "Mutation of both GIGYF2 and RQC components, such as Listerin/LTN1 and nuclear export mediator factor (NEMF), cause neurological disorders in mice." (PMID 34502507, 2021).
GIGYF2 also shares sentences with these, for which no sentence is quoted: glioma (3 papers); Parkinsonism (3); autism spectrum disorder (1); cardiovascular diseases (1); cognitive disorder (1); dementia (1); frontotemporal dementia (1); gastric cancer (1); hereditary ataxia (1); Hyperglycemia (1); mental disorder (1); ovarian cancer (1); schizophrenia (1); tumor (1); type 2 diabetes (1).